FOXP3 (forkhead box P3)
Diseases named in the same sentence as FOXP3 in open-access papers (continued):
Sharing a sentence is not in itself a finding about the gene and the disease.
autoimmune polyendocrine syndrome type 1 (3 papers, 2017 to 2023). Autoimmune polyendocrinopathy type 1, or APECED syndrome, is a genetic disease that manifests in childhood or early adolescence with a combination of chronic mucocutaneous candidiasis, hypoparathyroidism and autoimmune adrenal failure. "This relationship has been repeatedly established in monogenetic diseases as IPEX (FOXP3 mutations) and in autoimmune polyendocrine syndrome type 1 (AIRE mutations)." (PMID 28942732, 2017).
biliary tract cancer (3 papers, 2014 to 2023). "Hence, the objective of this meta-analysis is to assess the association between tumor infiltrating FoxP3+Tregs and the prognostic outcomes of individuals diagnosed with biliary tract cancer." (PMID 38115302, 2023). "The Meta-analysis was performed using STATA 17.0, and HR and its corresponding 95% CI were used to evaluate the correlation between FoxP3+ Tregs and the overall survival of patients with biliary tract cancer." (PMID 38115302, 2023). "The present study examines the correlation between tumor infiltrating FoxP3+ Tregs and OS in individuals diagnosed with biliary tract cancer." (PMID 38115302, 2023). "Nonetheless, our study provides pivotal, though broad, insights into the role of FoxP3+ Tregs in biliary tract cancer prognosis." (PMID 38115302, 2023). "The varied prognostic implications of FoxP3+ Tregs in different biliary tract cancers suggest a tailored treatment approach." (PMID 38115302, 2023). "This study aimed to explore the value of tumor-infiltrating Forkhead box P3(FoxP3+) regulatory T cells (Tregs) in evaluating the prognosis of biliary tract cancer." (PMID 38115302, 2023). "The antibody reacting with the N-terminus of Foxp3 highlighted carcinoma cells and Treg cells in 39% of biliary tract cancers while the antibody reacting with the C-terminus of Foxp3 detects only the mononuclear cells that correspond to Treg cells." (PMID 25132998, 2014). "Therefore, there may be a negative feedback mechanism of FoxP3+Tregs immunosuppression in TME of biliary tract cancer, which weakens the immunosuppressive effect of FoxP3+Tregs to some extent." (PMID 38115302, 2023). "The density of Foxp3- CD4+ helper T cells in the tumor margin rather than the tumor center and stroma has previously shown the best capacity for predicting the treatment response in biliary tract cancer patients, and the tumor margin may be the main site of the immune response in these cases." (PMID 36237314, 2022).
breast adenocarcinoma (3 papers, 2016 to 2024). "We also use 88 duplicate images of the 64-channel CODEX Human FFPE breast adenocarcinoma and test Mistic on seven channels: Keratin14, FoxP3, CD34, CD8, CD3e, CD68, and perlecan." (PMID 35845830, 2022).
diphtheria (3 papers, 2017 to 2022). A Gram-positive bacterial infection caused by Corynebacterium diphtheriae. "To evaluate the significance of Tregs for CLL progression we used DEREG transgenic mice with depletion of FoxP3+ CD4+ Tregs by treatment with diphtheria toxin (DT)." (PMID 35296093, 2022).
ductal carcinomas (3 papers, 2012 to 2022). "In ductal carcinoma, a FOXP3+/CD4+ > 1 was significantly associated with better survival (p = 0.0005)." (PMID 22471961, 2012). "In order to obtain insights into the nature of FOXP3+ cells associated with favorable prognosis in ductal carcinoma, TMA slides were stained with anti CD3 and anti CD163 Abs." (PMID 22471961, 2012). "Remarkably however, a ratio > 1 of total FOXP3+/CD4+ TILs in ductal carcinoma appears to represent an independent favorable prognostic factor." (PMID 22471961, 2012). "FOXP3 expression was significantly lower in large tumors (> 2 cm; rFOXP3 = − 0.38, p = 0.018) and in lobular carcinomas (rFOXP3 = − 0.59, p = 0.015), compared with ductal carcinomas (p < 0.001)." (PMID 31391067, 2019). "In ductal carcinomas, a significant (p < 0.001) association between higher total and intratumoral numbers of CD4+ and FOXP3+ lymphocytes and histological grade could be observed." (PMID 22471961, 2012). "Significantly (p < 0.001) higher numbers of total and intratumoral CD4+ and FOXP3+ TILs were detected in ER negative as compared to positive ductal carcinomas." (PMID 22471961, 2012). "High grade (G3) and estrogen receptor (ER) negative ductal carcinomas displayed significantly (p < 0.001) higher CD4+ and FOXP3+ lymphocyte infiltration while her2/neu over-expression in ductal carcinomas was significantly (p < 0.001) associated with higher FOXP3+ TIL counts." (PMID 22471961, 2012).
duodenal ulcer (3 papers, 2014 to 2024). An ulcer in the duodenal wall. "Consistent with our results, omeprazole treatment increases the frequency of CD4+ CD25+ FoxP3+ Treg cells and decreases the frequency of CD4+ IL-17A+ T cells among peripheral blood mononuclear cells (PBMCs) of patients with duodenal ulcers." (PMID 39247190, 2024).
fibrosarcoma (3 papers, 2007 to 2023). A malignant mesenchymal fibroblastic neoplasm affecting the soft tissue and bone. "DEREG (Foxp3-DTR-EGFP) mice were inoculated with CMS5 fibrosarcoma tumor cells, and Tregs were depleted by injecting diphtheria toxin (DT)." (PMID 37407600, 2023). "In the study described herein, we conducted a broad analysis of chemokine expression by MCA-induced fibrosarcomas and a side-by-side analysis of Foxp3+ and Foxp3− CD4+ T cells in terms of their phenotype and migratory capacity." (PMID 25495686, 2015). "These fibrosarcomas were strikingly infiltrated with FoxP3+ regulatory T cells implying that these cells impinge upon immune-mediated rejection of the tumour." (PMID 17565340, 2007). "We first wished to determine whether Foxp3+ T cells were more likely to migrate to carcinogen-induced fibrosarcomas compared with Foxp3− T cells." (PMID 25495686, 2015). "We next wished to address whether the chemokines attracting Foxp3+ and Foxp3− T cells to the fibrosarcomas were the same or distinct in nature." (PMID 25495686, 2015). "Therefore, having established the chemokine profile of the fibrosarcomas under study, we next sought to quantify the proportions of tumour-infiltrating CD4+ T cells (both Foxp3+ and Foxp3−) that expressed the corresponding chemokine receptors for these chemokines." (PMID 25495686, 2015).
gallbladder cancer (3 papers, 2018 to 2023). "The findings of the study indicated that the presence of FoxP3+ Tregs in patients with gallbladder cancer was associated with an unfavorable outcome (HR = 1.55, 95% CI 1.11 to 2.00; P < .001)." (PMID 38115302, 2023). "Our meta-analysis reveals that high infiltration of FoxP3 + Tregs is significantly associated with reduced overall survival in gallbladder carcinoma, endorsing their use as a prognostic biomarker for this subtype." (PMID 38115302, 2023). "Our findings underscore the prognostic significance of FoxP3+ Tregs in biliary tract tumors, notably gallbladder cancer." (PMID 38115302, 2023). "Our findings indicate that elevated levels of tumor-infiltrating FoxP3 + Tregs correlate with decreased OS in patients with gallbladder carcinoma, supporting their role as a prognostic marker in this subtype." (PMID 38115302, 2023). "Their finding shows that the existence of CD4+ T cells is not adequate to propose a tumor in a milieu containing decreased CD8+ T cells and that Foxp3+ T cells might have a negative effect on the potential of CD8+ T cells for fighting against gallbladder cancer." (PMID 36326418, 2022).
Gastric MALT lymphoma (3 papers, 2012 to 2023). "The in vivo inhibition of FOXP3+ regulatory T cells indeed resulted in the regression of gastric MALT lymphoma." (PMID 36768631, 2023). "Most of the tumor-infiltrating CD4+ cells in gastric MALT lymphoma were shown to be FOXP3+ Tregs, and these Tregs were recruited by tumor cells through the chemokines CCL17 and CCL22, secreted by FOXP3+ Tregs." (PMID 30999581, 2019). "In summary, our results show that gastric MALT lymphoma patients with high number of tumor infiltrating FOXP3+ cells have better response to eradication therapy." (PMID 23284739, 2012). "Gastric MALT lymphoma patients responding to bacterial eradication therapy had higher number of FOXP3+ cells at study entry." (PMID 23284739, 2012). "To further characterize the role of Treg cells in gastric MALT lymphoma, we analyzed a consecutive series of patients with gastric MALT lymphoma by quantifying the number of infiltrating CD3+ and FOXP3+ cells at diagnosis, and by describing the distribution pattern of FOXP3+ cells within the tumor." (PMID 23284739, 2012).
Glucose intolerance (3 papers, 2010 to 2022). Glucose intolerance (GI) can be defined as dysglycemia that comprises both prediabetes and diabetes. "In horses a relative abundance of Prevotellaceae disposes for a high expression of the Treg marker FoxP3, while a high relative abundance disposes for glucose intolerance in mice." (PMID 35417506, 2022). "The fact that it took so long for glucose intolerance to occur could perhaps be due to the concomitant increase in FOXP3 expression in adipose tissue, which indicates that regulatory T-lymphocytes are present, likely in an attempt to suppress inflammation." (PMID 21085605, 2010).
HCMV infection (3 papers, 2018 to 2024). "Noteworthy, HCMV infections and reactivations also promoted significantly higher frequencies of CD4+/CD25+/FoxP3+/CD45RA− regulatory T cells (Tregs) (INF Vs." (PMID 30524448, 2018). "HCMV infection of EVT did not diminish the ability of EVT to increase FOXP3+ and PD1HI Tregs, suggesting that HCMV infection does not alter the capacity of EVT to promote immune tolerance." (PMID 31921098, 2019).
heart failure (3 papers, 2017 to 2024). Inability of the heart to pump blood at an adequate rate to meet tissue metabolic requirements. "In a study of mouse models with heart failure, CD4+ Foxp3+ Tregs were found to expand robustly in the heart and circulation for adverse cardiac remodeling, resulting in the suppression of circulating CD4+ T cells and systemic inflammation." (PMID 37273870, 2023). "Circulating Tregs in patients with chronic heart failure have a significantly lower frequency, impaired function and reduced Foxp3 expression, and this phenomenon is not related to the aetiology of heart failure." (PMID 39917605, 2024).
Hepatic steatosis (3 papers, 2021 to 2025). Steatosis is a term used to denote lipid accumulation within hepatocytes. "Simultaneous blocking of CD25 or IL-17A and IL-17F shifted the TH17/Foxp3+ TREG imbalance from MCD diet-induced TH17 dominance to Foxp3+ TREG dominance and also decreased hepatic steatosis and inflammation." (PMID 34463867, 2021). "The results show that the supplemented animals had a higher frequency of Foxp3+ CD4+ (Treg) cells in mesenteric lymph nodes, less hepatic steatosis, higher levels of MDA, lower levels of vitamin E, and differences in the size of muscle fibers compared to non-supplemented IL−10−/− mice." (PMID 38474762, 2024).
hookworm infection (3 papers, 2011 to 2024). "We show that this accumulation also occurs during a short-term (1 week) oral gluten challenge, and that hookworm infection suppressed the increase of circulating CD4+CD25+Foxp3+ cells during this challenge period." (PMID 21949691, 2011). "Using Foxp3 as a marker of Tregs, we showed that gluten challenge induces an expansion of mucosal Foxp3+ cells in celiac sufferers irrespective of their hookworm infection status." (PMID 21949691, 2011). "Unfortunately functional assays of CD4+Foxp3+ suppression were not within the scope of this study, so we cannot say whether the hookworm infection increased suppressive ability and so suppressed inflammatory cytokine production." (PMID 21949691, 2011). "While studies in experimental models have provided evidence for increased FOXP3+ (forkhead box P3 transcription factor) Treg function during different helminth infections, the role of Tregs cells in human hookworm infection is still poorly understood and has not been addressed." (PMID 22087344, 2011). "In order to determine the possible effect of Treg cells on the immune response during hookworm infection, functional assays were designed to evaluate whether CD4+CD25+FOXP3+ Treg cells could modulate the in vitro cellular proliferation of CD4+ and CD8+ lymphocytes after parasite antigen stimulation." (PMID 22087344, 2011).
hydrops (3 papers, 2015 to 2024). "In a second family, a different FOXP3 mutation was identified in two miscarried monochorionic twin male fetuses, who died at 21 weeks of gestation due to hydrops; the fetuses demonstrated CD3+ infiltrating lymphocytes in their pancreases." (PMID 25999944, 2015). "IPEX (due to FOXP3 mutation leading to Treg cell deficiency), usually appearing in the first months of life, was recently observed in miscarried fetuses with hydrops who presented with CD3+ infiltrating lymphocytes in the pancreas." (PMID 25999944, 2015). "Additionally, at the Children’s Hospital of Philadelphia, in the same family, two miscarried fetuses who died due to hydrops were identified as carrying another FOXP3 mutation (Sara L. Reichert, personal communication, 2014)." (PMID 25999944, 2015). "Methotrexate administration resulted in increased levels of TNF-α, MPO, GATA3, caspase-3, and pulmonary edema indices, while reducing the levels of TAC, SOD, Gpx, IL-10, T-bet, and FOXP3." (PMID 38245672, 2024).
Intestinal infections (3 papers, 2011 to 2022). "Gliadins caused phosphorylation of STAT3 in PBMCs, and it can be speculated that constant stimulation of the immune system (e.g., by chronic inflammation or gastrointestinal infection) may alter tightly controlled activation of STAT3 and differentiation of Foxp3+ regulatory T cells." (PMID 36296938, 2022).
intestinal inflammation (3 papers, 2012 to 2024). "Thirdly, over-expression of T-bet in CD4+ T cells could directly inhibit the expression of FoxP3, because Th1 polarization is reported to underlie the pathogenesis of intestinal inflammation 24–26." (PMID 25219397, 2015).
laryngeal carcinoma (3 papers, 2020 to 2022). Carcinoma that arises from the laryngeal epithelium. "Oxaliplatin-treated primary laryngeal cancer cell-pulsed DCs increased the IFN-γ-producing CD8+ T cells and suppressed CD4+CD25+FoxP3+ Tregs." (PMID 36131787, 2022). "Pre-treatment biopsies from 80 oropharyngeal, 52 hypopharyngeal, and 29 laryngeal cancer patients were collected in a tissue microarray (TMA) and immunohistochemically stained for T-cell markers CD3, CD4, CD8, FoxP3, and PD1, and for immune checkpoint PD-L1." (PMID 31980916, 2020). "Finally, we evaluated the effects of DCs that were cocultured with oxaliplatin-treated primary laryngeal cancer cells on the populations of T cells, including IFN-γ-producing CD8+ T cells and CD4+CD25+FoxP3+ Treg cells." (PMID 36131787, 2022).
laryngeal squamous cell carcinoma (3 papers, 2014 to 2022). A squamous cell carcinoma that arises from the larynx. "The chemokine receptors CCR6 and CCR7 have been reported to be involved in the presence of Foxp3+ Treg cell in favor of progression of laryngeal squamous cell carcinoma." (PMID 30216450, 2019).
lobular carcinomas (3 papers, 2012 to 2022). "For 480 ductal and for 72 lobular carcinoma samples FOXP3+/CD4+ cell ratios and overall survival data were available." (PMID 22471961, 2012). "Increased numbers of total CD4+ and FOXP3+ TIL were observed in ductal, as compared with lobular carcinomas." (PMID 22471961, 2012). "All her2/neu over-expressing lobular carcinomas regardless of their hormone receptor status showed an increased infiltration by intratumoral FOXP3+ cells (p = 0.002)." (PMID 22471961, 2012).
lymphoproliferative autoimmune syndrome (3 papers, 2009 to 2021). "T cell-specific ablation of Foxp3 resulted in a lymphoproliferative autoimmune syndrome identical to that observed in Foxp3-deficient mice." (PMID 19751267, 2009). "Mice lacking Foxp3 usually die of lethal lymphoproliferative autoimmune syndrome, and humans with FOXP3 mutations suffer from an autoimmune syndrome called IPEX." (PMID 34531852, 2021). "This lead to FOXP3 mRNA instability, a 90% decrease of FOXP3 protein expression, and as a consequence these mice succumbed to aggressive lymphoproliferative autoimmune syndrome, indicating that Treg cell function directly correlates with the amount of FOXP3 protein expressed." (PMID 26441996, 2015).
male infertility (3 papers, 2019 to 2023). The inability of the male to effect fertilization of an ovum after a specified period of unprotected intercourse. "Recently, we have demonstrated that FOXP3 variants cause male infertility and FOXP3stimulates the proliferation and inhibits the apoptosis of human SSCs." (PMID 33802813, 2021). "FOXP3 was reported to play important roles during regulatory T-cell development in previous studies, and FOXP3 polymorphisms are associated with human female endometriosis and male infertility." (PMID 36602025, 2023). "Notably, we have revealed that 10 of 300 NOA (3.3%) patients have FOXP3 variants, which is 10 time higher than other gene variants in NOA patients, suggesting that FOXP3 mutation is closely associated with male infertility." (PMID 33802813, 2021). "Identification of male infertility-associated PV in FOXP3 and the investigation of its precise defects in molecular structures and functions resulting from specific PV could provide the definitive and causative link between FOXP3 dysfunction and male infertility in human." (PMID 31855573, 2019). "Herein, we initiated to screen the PV of FOXP3 in clinical NOA patients and revealed the importance of FOXP3 in human male infertility." (PMID 31855573, 2019). "To explore the functional importance of FOXP3 in human male infertility, we screened for potential PV of FOXP3 in 314 NOA patients and 14 OA controls." (PMID 31855573, 2019). "Nevertheless, the understanding in the relationship of FOXP3 and male infertility is quite limited." (PMID 31855573, 2019). "The complex regulatory network connecting FOXP3 and cytokines may account for the dysfunction of mutant FOXP3 protein in male infertility." (PMID 31855573, 2019).
measles (3 papers, 2009 to 2022). A highly contagious viral infection caused by the measles virus. "Although MV infection could induce different and nonexclusive mechanisms that may contribute to the generalized immunosuppression, the modulation of Foxp3+ Treg homeostasis, may be the essential step in measles immunopathogenesis." (PMID 19319188, 2009). "In infants vaccinated against measles and Diphteria/Tetanus/Pertussis (DTP), a (relatively weak) negative association between the number of CD127Lo FoxP3+ Tregs present in the periphery and the antibody response to measles vaccination, but not DTP vaccination (Diph-Tet-Pert) was shown." (PMID 36466865, 2022). "The inverse correlation between the circulating CD4+FOXP3+CD127− Tregs post-DTP vaccination and the postvaccination IFN-γ:IL-10 ratio in TT and measles peptide cultures, but not PPD or αCD3/αCD28, may support a vaccine-specific immunoregulatory role." (PMID 28855899, 2017).
metabolic syndrome (3 papers, 2020 to 2025). A cluster of metabolic risk factors for CARDIOVASCULAR DISEASES and TYPE 2 DIABETES MELLITUS. "We also investigated the role of dyslipidemia in the observed changes in T-bet+Foxp3+ cell differentiation and IFN-γ production by memory CD4+ T cells of HDs and SLE patients." (PMID 33329581, 2020).